BATF3 (basic leucine zipper ATF-like transcription factor 3)
Diseases named in the same sentence as BATF3 in open-access papers (continued):
Sharing a sentence is not in itself a finding about the gene and the disease.
infection (34 papers, 2011 to 2025). The state of being infected such as from the introduction of a foreign agent such as serum, vaccine, antigenic substance or organism. "Ranked regulon activity analysis of key TFs during early infection further confirmed the predominant contributions of BATF3, MAF, and CREB3 within AntiviralMac and SusceptibleMac populations." (PMID 40723441, 2025). "Meanwhile, it should be noted that pathogen infection or IL-12 administration can restore cDC1 in BATF3-deficient mice." (PMID 35693801, 2022). "In BATF3-deficient mice, Treg cell induction was attenuated after infection with a gastric pathobiont, Helicobacter pylori." (PMID 35693801, 2022). "To analyze the role of Batf3 deficiency in the evolution of VL, we carried out a comparative analysis of the development of the infection in the liver with parasites expressing the luc gene between Batf3−/− mice and their corresponding littermate controls." (PMID 33362772, 2020). "Intradermal infection of a C57BL/6 mouse strain deficient in Batf3, resulted in an exacerbated evolution of the CL disease." (PMID 33362772, 2020). "Regardless, morbidity and disease severity remained almost completely unaffected in Batf3-deficient compared to wild-type mice, while Csf2−/− mice succumbed to infection." (PMID 24699679, 2014). "We therefore exposed Batf3−/− mice to A. fumigatus and measured lung fungal burden at 12, 24, and 48 h post infection." (PMID 40980891, 2025). "Representative GMS-stained lung tissue from WT BL/6 (left) and Batf3−/− mice (right) 24 h post-infection supports higher A. fumigatus levels in the former." (PMID 40980891, 2025). "In contrast to the previous four DC subsets, we observed significantly increased levels of inf-cDC2s in Batf3−/− mice 24 h post-infection." (PMID 40980891, 2025). "At late stages of infection, Batf3 deletion leads to 100-fold and 10-fold increased fungal burden in the lung and brain, respectively." (PMID 39254303, 2024). "In the liver, BATF3/BDCA2+ DCs that were ACE2+ exhibited an even higher likelihood of infection than ACE2– BATF3/BDCA2+ DCs." (PMID 35022412, 2022). "In our study, we did not observe differences in IFN-γ production from αβ T cells or parasite load in Batf3-/- mice compared to wild-type mice early after infection." (PMID 34699567, 2021). "We previously showed that archived antigen obtained from the polyI:C/anti-CD40-based vaccine is transferred from LECs to migratory Batf3-dependent cDC1s 2 weeks after infection." (PMID 33843587, 2021). "Batf3−/− mice succumbed to infection with RHΔku80Δrop5 parasites upon specific depletion of T cells, confirming that clearance relied on an efficient T cell response." (PMID 32669460, 2020). "Of note, the reduction observed in the MLN and spleen of Batf3–/– mice after foodborne InlAMLm was much less substantial than that reported after i.v. infection." (PMID 33042159, 2020). "One cohort of Batf3–/– mice received an infection dose of 1 × 1011 CFU while another cohort of Batf3–/– were treated with 20 mg streptomycin by gavage prior to infection with 2 × 105 CFU InlAMLm." (PMID 33042159, 2020). "In contrast, Batf3−/− mice infected with RHΔku80Δrop5 were initially unable to control growth but subsequently resolved and cleared the infection." (PMID 32669460, 2020). "Batf3−/− naive recipient mice received either CD4 or CD8 T cells from Batf3−/− naive or infected mice 1 day before infection with RHΔku80Δrop5 parasites and were monitored for 30 days." (PMID 32669460, 2020). "In Batf3−/− mice a single dose of IL-12 reduced parasite levels significantly, and a second treatment 1 day after infection further delayed and limited the growth of RHΔku80Δrop5." (PMID 32669460, 2020). "Batf3−/− mice showed very low, although detectable, titers of the IgG2c subclass antibodies throughout the infection process." (PMID 33362772, 2020).
infection (continued). "Despite reduced activation and IFN-γ production by NK cells, Batf3−/− mice showed greater recruitment of neutrophils and Ly6Chigh inflammatory monocytes to the site of infection than did wild-type mice." (PMID 32669460, 2020). "Subsequent restoration of pathogen burden through increased i.v. infection dose was able to rescue Lm-specific CD8 T cell responses in Batf3–/– mice, suggesting that other antigen presenting cells are capable of eliciting a CD8 T cell response to Lm infection." (PMID 33042159, 2020). "Here, we examined the ability of Batf3−/− mice to control infection with a highly attenuated parasite mutant to distinguish between a requirement during innate (IL-12 production) and that during adaptive (cross-presentation to CD8 T cells) immunity." (PMID 32669460, 2020). "To test these alternative models, we depleted CD4 or CD8 T cells in Batf3−/− mice and evaluated infection with RHΔku80Δrop5 parasites." (PMID 32669460, 2020). "Due to the finding that Batf3–/– mice display defects in maximal bacterial accumulation in the MLN after foodborne InlAMLm infection, the DC subsets which contain InlAMLm in the MLN after foodborne infection were determined." (PMID 33042159, 2020). "Wild-type as well as Batf3−/− mice survived the secondary challenge with wild-type parasites, suggesting that adaptive responses to primary infection were sufficient to induce long-term memory response." (PMID 32669460, 2020). "As such, the role of cDC1 in the transit of InlAMLm and establishment of productive infection after foodborne infection was evaluated in Batf3–/– mice, which lack resident CD8α+ and migrant CD103+ cDC1." (PMID 33042159, 2020). "Batf3−/− mice, which lack CD8α+ and CD103+ cDCs, are therefore highly susceptible to infection with T. gondii due to inadequate early IL-12 production." (PMID 32669460, 2020). "Nevertheless, Batf3−/− mice uniformly survived infection by the RHΔku80Δrop5 strain, suggesting another mechanism was able to restore the ability to control infection." (PMID 32669460, 2020). "Consistent with the results obtained for Batf3−/− infection with the avirulent strain RHΔku80Δrop5, depletion of CD4 T cells before challenge with RHΔku80 significantly affected survival of Batf3−/− mice." (PMID 32669460, 2020). "The frequency of this population in the MLNs increased strongly upon infection, and this was highly dependent on BATF3." (PMID 31188899, 2019). "We also observed clear BATF3-dependent differences in infection-induced cytokine expression in the liver." (PMID 31188899, 2019). "The increase in gastric LP pTreg frequencies upon infection can largely be attributed to an increase in these Tbet+ RORγt+ pTregs, and is highly dependent on BATF3." (PMID 31188899, 2019). "Strikingly, we find that not only the expansion and/or recruitment of Th1 cells, but also of peripherally induced, neuropilin-negative regulatory T-cells to sites of infection requires BATF3-dependent DCs." (PMID 31188899, 2019). "Although we found the frequencies of CD4+ Foxp3+ Tregs to be comparable in the gastric LP of WT and BATF3-/- mice, both in the steady state and upon infection, the composition of the Treg compartment differed substantially as a result of BATF3 deficiency." (PMID 31188899, 2019). "The stronger Tc1 cell responses observed in Batf3−/− mice suggested that the deletion of Batf3 activated CD8+T cells unexpectedly during the natural infection of schistosomes." (PMID 28646891, 2017). "Surprisingly, there was still a small amount of CD8α+ DCs in the spleen of Batf3−/− mice at 9 weeks post-infection." (PMID 28646891, 2017). "The stronger Tc1 cell responses observed in Batf3−/− mice suggested that the deletion of Batf3 activated CD8+T cells unexpectedly during the natural infection of schistosome." (PMID 28646891, 2017).
infection (continued). "Opposed to previous studies, our findings suggest that during the infection of S. japonicum, the deletion of Batf3 activates CD8+T cells to secrete IFN-γ and attenuate liver pathological damage in mice through immune regulation." (PMID 28646891, 2017). "The stronger Tc1 cell responses observed in Batf3−/− mice suggested that the deletion of Batf3 resulted in more activation of CD8+T cells unexpectedly during the natural infection of schistosomes." (PMID 28646891, 2017). "Optimal generation of Trm cells following rVACV infection requires unique priming signals provided by Batf3-dependent DCs that favour T-bet expression and LN retention." (PMID 28714465, 2017). "CD8α+ DCs were only required to cross present YopE peptide if infection was carried out with strain ΔBmE, since the levels of ET cells in the Batf3-/- mice infected with ΔBmE decreased to the levels seen in mice left uninfected." (PMID 26468944, 2015). "Cross-presentation appeared to be the sole pathway used to present the secreted YopE to CD8+ T cells during infection with ΔBmE, since ET cell numbers in Batf3-/- mice infected with this mutant were similar to those in mice left uninfected." (PMID 26468944, 2015). "In particular, there is a significant expression of Batf3 in microglia during infection and LPS challenge, and thus, it is possible that Batf3 may be important in regulating the activity of these brain-resident macrophage populations." (PMID 39254303, 2024). "We also discovered that BATF3/BDCA2+ DCs exhibited a higher tendency for infection over BATF3/BDCA2– cells in all organs under consideration and that only in the liver, CD206+ macrophages were more likely to be infected than CD206– cells while in the lungs and heart, the converse was true." (PMID 35022412, 2022). "While Lm burden is low in the spleen and liver of Batf3–/– mice after i.v. infection, Batf3 deficiency did not reduce InlAMLm burden in the small intestine or MLN 1 day after infection." (PMID 33042159, 2020). "Similarly, Batf3−/− mice also succumbed to infection with the RHΔku80 strain, displaying comparable uncontrolled growth of the parasite." (PMID 32669460, 2020). "However, Batf3−/− mice began to clear infection by day 5, before the reappearance of CD8α+ cDCs, suggesting that clearance was not due to the reappearance of CD8α+ cDCs, but rather due to some other mechanism." (PMID 32669460, 2020). "We next addressed whether the differences in pTreg recruitment to the site of infection in WT and BATF3-/- mice were attributable to differential priming of Tregs in the MLNs upon H. pylori infection." (PMID 31188899, 2019). "Interestingly, BATF3-/- mice had reduced local Th1 responses upon infection as determined by intracellular cytokine staining for IFN-γ and by quantification of IFN-γ transcript levels in the gastric mucosa." (PMID 31188899, 2019). "We therefore tested the contribution of cDC1 during FVC infection (r.o.)using Batf3−/− mice." (PMID 30595553, 2019). "We detected a small amount of CD8α+ DCs in the spleen of Batf3−/− mice at 9w post-infection." (PMID 28646891, 2017). "In addition, the percentage of Tc2 cells in the spleen of both Batf3−/− and B6 mice increased slowly since infection, and then rapidly increased to the top level at 6 weeks post-infection." (PMID 28646891, 2017). "Then we detected a small amount of CD8α+ DCs in the spleen of Batf3−/− mice at 9w post-infection." (PMID 28646891, 2017). "To investigate whether microbial glycolipid antigen presentation also required CD8α+ DCs in the setting of infection, we compared the lung burdens of Batf3−/−and WT mice after intranasal infection with S. pneumoniae." (PMID 24412610, 2014). "However, this commitment can also be achieved in the absence of Batf3 by infection-associated induction of IL-12, which promotes expression of Batf, enabling cDC1 development in Batf3−/− mice." (PMID 33997687, 2021).
infection (continued). "However, as can be deduced from the radiance values from week 7 to the end of the assay, at the late phase of the infection, parasite burden reached a plateau in Batf3−/− mice, suggesting that they have an impaired ability to control hepatic parasite multiplication (weeks 7–10)." (PMID 33362772, 2020). "Interestingly, and as observed after infection of mice with H. pylori, the expression of the chemokines CXCL9 and CXCL10 was strongly reduced in BCG-infected BATF3-deficient compared to WT mice, whereas CXCL11 expression was unaffected by the BCG infection or the mouse genotype." (PMID 31188899, 2019). "Batf3-dependent CD8+ DC and peripheral CD103+ DC have been shown to be an essential IL-12 source during infection." (PMID 39440975, 2024). "Additionally, neonatal mice that lacked transcription factor Batf3 (Batf3 drives the development of CD103+ DCs) were more susceptible to infection and could not clear infection." (PMID 37325809, 2023). "Conventional DC1 cells (XCR1, BATF3 -expressing PBMC myeloid population 6) were less abundant than cDC2s and changed relatively little in abundance during infection." (PMID 35271298, 2022). "Altogether, these findings indicate that Batf3 is needed to generate these responses and suggest cDC1 are needed for the induction of effector CD8 T cells after foodborne InlAMLm infection." (PMID 33042159, 2020). "Seven days after infection, the frequency and numbers of TCD8+ producing IFN-γ in response to the B8R and A8R epitopes were equivalent in wild-type and Batf3-/- mice." (PMID 26107264, 2015). "We did observe proliferation of OT-1 in the D-LN after infection with NP-S-EGFP, but the proliferation observed was equivalent in wild-type and Batf3-/- mice, indicating that CD8α + DC are dispensable for initiation of an OVA-specific TCD8+ response." (PMID 26107264, 2015). "Similar to WT STm infection, genes involved in the regulation of immune responses (ATF3, BATF3, ETS2, IRF9, NFκB2, MAFA, TNFAIP3), effector functions, (CCL4, CD200L, CD40, CD72, CD80, IL18) and TLR signaling, (EAF2, TLR15, TRAF3IP2, TOLLIP) were upregulated after ΔprgH STm infection in both models." (PMID 37854334, 2023). "Despite their ability to restore pathogen burden, neither high-dose infection nor pretreatment with streptomycin were capable of rescuing InlAMLm-specific CD8 T cell responses in the MLN or spleen of Batf3–/– mice." (PMID 33042159, 2020). "However, in both Batf3−/− and wild-type mice, CD4 memory T cells contributed to the protection of mice after challenge with lethal infection." (PMID 32669460, 2020). "In summary, Batf3−/− mice show increased parasite burden, inflammation, and systemic IFN-γ levels after infection by RHΔku80Δrop5 parasites relative to wild-type mice, but rather than succumbing to infection, they are able to clear the pathogen during the first weeks of infection." (PMID 32669460, 2020). "We observed a modest but reproducible increase in the frequencies of neuropilin-negative pTregs expressing Tbet and RORγt as a consequence of neonatal, but not adult infection in WT mice; this increase was dependent on BATF3." (PMID 31188899, 2019). "The gastric LP of BATF3-/- animals exhibited strongly reduced numbers of CD103+CD11b- DCs, but was populated by normal complements of CD103+CD11b+ DCs, D11b+ DCs and macrophages, both in the steady state and during infection." (PMID 31188899, 2019). "However, when the infection dose administered to Batf3–/– mice was increased, bacterial burden and Lm-specific CD8 T cell responses were restored suggesting that the defect in the CD8 T cell response was due to diminished bacterial burdens in Batf3–/– mice." (PMID 33042159, 2020). "In addition, compared with B6 mice, Lm-infected B6.Il18−/−, B6.Nlrp3−/−, and B6.Batf3−/− mice showed reduced levels of serum IFNγ without any effect on the bacterial burden at 24 h post-infection, demonstrating that these factors also regulate IFNγ production during Lm infection." (PMID 35053151, 2021).
infection (continued). "Finally, InlAMLm-specific CD8 T cell responses were diminished in Batf3–/– mice and restoration of pathogen burden was unable to restore InlAMLm-specific CD8 T cell responses, suggesting a dynamic role for DC subsets in driving effector CD8 T cell responses after foodborne InlAMLm infection." (PMID 33042159, 2020). "Others and we have shown that, in the absence of Batf3-depedendent cDC1, there is a poor IFN-γ response in the murine model of CL due to infection with L. major." (PMID 33362772, 2020). "The importance of CD8α DCs and NK cells was revealed from experiments conducted in mice lacking CCR5, IRF8, or basic leucine zipper transcription factor ATF-like 3 (BATF3), a transcription factor required for the development of CD8α DCs, as all of them succumb quickly to the infection." (PMID 33178630, 2020). "In BATF3−/− mice lacking CD8α+ DCs, ISG15 fails to induce an IL-1β increase during Toxoplasma infection, as seen in B6 mice, demonstrating that ISG15 induces IL-1β–producing CD8α+ DCs at the site of infection." (PMID 29891555, 2018).
bacterial infection (4 papers, 2019 to 2024). "To assess whether BATF3-dependent DCs also contribute to the control of systemic bacterial infection, we infected WT and BATF3-deficient mice with M. bovis BCG." (PMID 31188899, 2019). "Recent evidence suggests that BATF3-deficient CD8+ T cells exhibit defects in T cell memory formation, reduced proliferation rates, and increased cell death following viral or bacterial infections." (PMID 38297190, 2024). "Of note, the cDC1 compartment can be completely restored in Batf3−/− mice through bacterial infection or administration of IL-12, in which case Batf compensates for the lack of Batf3." (PMID 33997687, 2021). "The combined results suggest that the (Th1-dependent) control of mucosal as well as systemic bacterial infections requires BATF3-dependent DCs." (PMID 31188899, 2019). "This highlights the involvement of Batf3 in the generation of Th1 immunity against different Leishmania species, as also happens with other protozoan parasites such as Toxoplasma gondii, or in mucosal or systemic bacterial infections." (PMID 33362772, 2020).
inflammation (2 papers, 2021 to 2025). Aberrant reaction of the microcirculation characterized by movement of fluid and leukocytes from the blood into extravascular tissues. "An agonistic peptide that stimulates Qa-1b-restricted regulatory TCRαβ+CD8αα+ T cells confers protection in the acute model of colonic inflammation in a Qa-1b- and Batf3-dependent manner, and enhances expression of known barrier-protective genes in distal colon." (PMID 34911745, 2021).
infectious disease (1 paper, 2020). A disorder directly resulting from the presence and activity of a microbial, viral, or parasitic agent in humans. "Our results reinforce the implication of Batf3 in the generation of type 1 immunity against infectious diseases." (PMID 33362772, 2020).
BATF3 also shares sentences with these, for which no sentence is quoted: Hodgkins lymphoma (5 papers); adult T cell leukemia (2); non-small cell lung carcinoma (2); acute myeloid leukemia (1); Allergy (1); Autoimmunity (1); Crohn disease (1); Cryptococcal meningitis (1); cytomegalovirus infection (1); diffuse large B-cell lymphoma (1); fibrosis (1); follicular lymphoma (1); glioblastoma (1); graft versus host disease (1); Hypercalcemia (1); hyperlipidemia (1); intestinal inflammation (1); intestinal T-cell lymphoma (1); latent infection (1); liver cancer (1); liver steatosis (1); lymphopenia (1); malignant brain tumor (1); meningitis (1); metabolic disorders (1); nonalcoholic fatty liver disease (1); pancreatic cancer (1); peripheral T-cell lymphoma (1); plasma cell neoplasm (1); Schistosomiasis japonica (1).
A further 2 diseases each share a sentence with BATF3 in 1 paper.